SEC22C (SEC22 homolog C, vesicle trafficking protein)
Description:
May be involved in vesicle transport between the ER and the Golgi complex.
Synonyms: SEC22L3; MGC13261; MGC5373
Tractability: Antibody: UniProt predicts a signal peptide or a membrane-spanning region. PROTAC: ubiquitination databases record sites on it.
Gene: Protein-coding gene on chromosome 3 (42,547,969 to 42,601,168, reverse strand). Ensembl gene ENSG00000093183.
Subcellular location: Endoplasmic reticulum membrane
Subcellular location (Human Protein Atlas): Golgi apparatus; Nucleoplasm
Pathways (Reactome):
Vesicle-mediated transport: COPII-mediated vesicle transport
Gene Ontology:
Molecular function: protein binding
Biological process: endoplasmic reticulum to Golgi vesicle-mediated transport
Cellular component: endoplasmic reticulum; membrane; endoplasmic reticulum membrane
Genetic constraint (gnomAD): Loss-of-function variants: 22 observed, 28.61 expected, observed/expected ratio (o/e) 0.77, 90% interval 0.55 to 1.1. The upper end of that interval is the gene's LOEUF score, 1.1, which puts it in group 4 of 6, group 1 being the genes least tolerant of losing a copy. Missense variants: 311 observed, 360.13 expected, observed/expected ratio (o/e) 0.86, 90% interval 0.79 to 0.95. Synonymous variants: 111 observed, 132.46 expected, observed/expected ratio (o/e) 0.84, 90% interval 0.72 to 0.98.
Homologues: Orthologues: chimpanzee SEC22C (99% identical), macaque SEC22C (97% identical), pig SEC22C (93% identical), dog SEC22C (91% identical), rabbit SEC22C (89% identical), mouse Sec22c (81% identical), rat Sec22c (81% identical), guinea pig SEC22C (79% identical), tropical clawed frog sec22c (54% identical), zebrafish sec22c (49% identical), Drosophila melanogaster Syb (8% identical), Caenorhabditis elegans snb-2 (5% identical), and 3 more. Paralogues in human: SEC22A (41% identical), SEC22B (21% identical), YKT6 (9% identical), VAMP4 (8% identical), VAMP7 (8% identical), VAMP2 (7% identical), VAMP1 (7% identical), VAMP8 (5% identical), VAMP3 (4% identical), VAMP5 (3% identical).
Diseases named in the same sentence as SEC22C in open-access papers:
SEC22C is named in the same sentence as 2 diseases in open-access papers, as found by Europe PMC text mining. Sharing a sentence is not in itself a finding about the gene and the disease.
SEC22C shares sentences with these, for which no sentence is quoted: cancer (1 paper); tumor (1).